RNU6-1049P (RNA, U6 small nuclear 1049, pseudogene)
Gene: Small nuclear RNA gene on chromosome 2 (130,109,204 to 130,109,310, reverse strand). Ensembl gene ENSG00000252223.
Homologues: Orthologues: macaque U6 (93% identical), macaque U6 (91% identical), guinea pig U6 (77% identical), dog U6 (74% identical), pig U6 (65% identical). Paralogues in human: RNU6-473P (99% identical), RNU6-617P (99% identical), RNU6-848P (99% identical), RNU6-127P (98% identical), RNU6-1239P (97% identical), RNU6-1268P (97% identical), RNU6-816P (97% identical), RNU6-1021P (93% identical), RNU6-286P (92% identical), RNU6-631P (92% identical), RNU6-749P (92% identical), U6 (92% identical), and 1288 more.